EZH2 (enhancer of zeste 2 polycomb repressive complex 2 subunit)
Diseases named in the same sentence as EZH2 in open-access papers (continued):
Sharing a sentence is not in itself a finding about the gene and the disease.
cancer (continued). "EZH2 functions in such various biological processes, which is the reason why it is related to many diseases, including cancer." (PMID 32723346, 2020). "Of all PKMTs, EZH2 has been the most studied and EZH2 inhibitors have already entered clinical trials in multiple cancer types." (PMID 33050946, 2020). "In sum, phosphorylation of EZH2 is important for oncogenesis and metastasis in numerous cancer types." (PMID 33308321, 2020). "Other epigenetic mechanisms such as histone deacetylation and aberrant expression of the Enhancer of zeste homolog 2 (EZH2) contribute to the control of PD-L1 expression in cancer cells by limiting transcription factor access to the PD-L1 promoter region." (PMID 32992658, 2020). "Inhibitors of DNMTs, HDACs, or other chromatin modifier complexes, such as EZH2 inhibitors, have increased the variety of therapeutic approaches for the treatment of cancer." (PMID 32492865, 2020). "The overexpression of EZH2 has been observed in a variety of cancers, and was correlated to cancer progression, metastasis and poor prognosis in various cancer types." (PMID 33304896, 2020). "This study suggests that SNHG1 inhibits the proliferation and metastasis of PCa cells by binding EZH2, and promotes the apoptosis and autophagy of cancer cells." (PMID 33194612, 2020). "In the current review, we show an overview of the molecular mechanisms and biological functions of EZH2 modifications in cancer progression." (PMID 33308321, 2020). "The impact of EGCG on histone methylation has so far been analyzed from the level of cancer cells and polycomb group (PcG) protein, particularly EZH2, but also Suz12, Mel18 and Bmi-1." (PMID 32429384, 2020). "EZH2 PTMs can influence EZH2 functions in several aspects, making it an attractive therapeutic target to prevent EZH2 functions in cancer." (PMID 33308321, 2020). "The expression, stability, localization, and activity of EZH2 can be disrupted through different mechanisms in patients with cancer." (PMID 33308321, 2020). "To explore the molecular mechanism of EZH2 overexpression in HCC, we analyzed the copy number variation of EZH2 gene in a PAN-cancer panel using the TCGA data set." (PMID 33168810, 2020). "Both EZH2 and KDM6B, two proteins with opposite catalytic activities, have previously been associated with cancer aggressiveness or EMT." (PMID 33291363, 2020). "It means that NSC745885 has potent anti-cancer effects through facilitating EZH2 ubiquitination-proteasome degradation." (PMID 33308321, 2020). "As the traditional oncogenic function of EZH2 is focused on inducer of cancer cell proliferation and development, further comprehensive research is necessary for defining the other role of EZH2, such as EMT process, invasion, and angiogenesis." (PMID 33291558, 2020). "After an integrative analysis of the TCGA data sets, we discover that the EZH2 somatic copy number alteration frequently occurs in different types of cancers." (PMID 33168810, 2020). "As EZH2 plays important roles in the pathophysiology of cancer, it becomes a potential target for cancer therapy." (PMID 32723346, 2020). "EZH2 dually enhances the migration and proliferation of cancer cells, and targeting this oncogene factor is a promising strategy in cancer therapy." (PMID 32545648, 2020). "EZH2 contributes to tumorigenesis and cancer progression, often through inactivation of tumor suppressor genes." (PMID 32760219, 2020). "In particular, HOTAIR along with several other lncRNAs such as HEIH, PCAT-1, and H19 etc., play oncogenic roles by interacting with PRC2 to recruit EZH2 to target genes in various cancers." (PMID 33003334, 2020). "Recently, increasingly more studies have revealed that EZH2 has a cancer-promoting effect, including the induction of the abnormal cell differentiation and promotion of cancer cell proliferation." (PMID 31966062, 2020).
cancer (continued). "This present review summarizes several main phosphorylation sites of EZH2 according to previous studies and related influence to their functions in cancer progression." (PMID 33308321, 2020). "Many pharmaceutical companies have developed EZH2 inhibitors in light of evidence that EZH2 can be a driver of human diseases including cancer." (PMID 33207561, 2020). "The translation of EZH2 inhibitors into clinical trials have shown preliminary evidence of clinical response (CR) in cancer." (PMID 32042336, 2020). "Since its discovery in 1996, only now has EZH2 been thought as an important histone methyltransferase in cancer progression." (PMID 33308321, 2020). "Given that EZH2 was overexpressed in many types of cancer, and inhibitors targeting EZH2 were also developed." (PMID 32206036, 2020). "EZH2 overexpression predicted poor prognosis in various cancers, suggesting its oncogenic role in tumorigenesis." (PMID 33121524, 2020). "Different types of EZH2 inhibitors have been developed, and there are a number of ongoing clinical trials of drugs targeting EZH2 in different cancer types." (PMID 32723346, 2020). "High levels of EZH2 were shown to correlate with aggressiveness and advanced disease in each of these cancer types." (PMID 32477007, 2020). "EZH2 performs a pivotal and essential function in maintaining cancer properties in Wnt/β-catenin signaling activation." (PMID 33033513, 2020). "Intriguingly, also many lncRNAs have been described to participate in the EZH2 oncogenic regulatory network, further highlighting the complex regulation of EZH2 activity in human cancer, and reinforcing its critical role in cancer progression." (PMID 31963578, 2020). "Consistent with dysregulation of PRC2 in several human cancers, a robust expression of EZH2, SUZ12, and EED proteins was seen on the western blots for all MCL cell lines analyzed." (PMID 32850364, 2020). "This review presents an overview of different roles of EZH2 modification and EZH2-PTMs crosstalk during tumorigenesis and cancer metastasis." (PMID 33308321, 2020). "Taken together, these reports suggest that ZRANB1, USP7, USP1 and USP36 can promote cancer development via the stabilization of EZH2 by deubiquitination." (PMID 33308321, 2020). "Due to the fundamental role of EZH2 in cancer progression, different inhibitors of EZH2 have been designed and tested for evaluation of efficacy." (PMID 32290543, 2020). "Given the evidence for EZH2 involvement in cancer, the development of EZH2-specific catalytic inhibitors (EZH2i) has been an active area of investigation for quite some years." (PMID 34968293, 2020). "Nevertheless, several studies demonstrated that MALAT1 augments the oncogenic activities of EZH2 in different types of cancer." (PMID 32760219, 2020). "Emerging evidences have suggested the involvement of lncRNAs in complexation with EZH2 and exerted epigenetic regulation in human cancers." (PMID 33160411, 2020). "Intriguingly, a significant number of studies evidenced a strict correlation of EZH2 overexpression with patient poor outcome and high aggressiveness in several cancer types." (PMID 31963578, 2020). "Another key gene, EZH2, is a histone methyltransferase subunit of a polycomb repressive complex, which is highly expressed in numerous cancers." (PMID 33381151, 2020). "Just like in human cancers, overexpression of EZH2 was found in canine lymphoma, melanoma, basal cell tumors, squamous cells carcinoma, and prostate and mammary cancer." (PMID 33194754, 2020). "EZH2 expression was verified in 40 NSCLC tissue cancer samples and their corresponding paracancerous tissues from our institute (TJMUGH) via RT-PCR." (PMID 33276757, 2020). "Consistently, our findings also confirmed that EZH2 was highly expressed in various cancer types, including HCC." (PMID 33121524, 2020). "Taken together, the data suggested CAMK2A mediated in vitro cancer phenotypes and drug resistance through reducing EZH2 and release of SOX2 from epigenetic repression." (PMID 32483123, 2020).
cancer (continued). "Nevertheless, there are still some challenges in direct targeting of EZH2 in cancers due to its various roles." (PMID 33665162, 2020). "Accumulating all these summarized results, the expression of EZH2 is upregulated in different types of cancer, and its inhibition is required by different miRNAs and drugs to reduce cancer progression." (PMID 33014831, 2020). "SMARCA4 has an antagonistic relationship with histone methyltransferase EZH2 (part of the PRC2 complex), which indeed is essential for survival and growth of SMARCA4-deficient cancer cells." (PMID 31996670, 2020). "Intriguingly, we observed that the expression of EZH2 was upregulated in different cancers, indicating the dysregulation of EZH2-mediated signaling pathway was a common phenomenon in tumorigenesis." (PMID 33168810, 2020). "From cancer models, the regulation of EZH2 expression and function is more fully elucidated and how its modulation in both CD4+ and CD8+ T cells can, directly and indirectly, impact the CD8+ T cells response." (PMID 33117406, 2020). "Taken together, EZH2 induces cancer drug resistance by regulating downstream gene expression with different mechanisms." (PMID 32859239, 2020). "EZH2 is a promising anticancer target with a well-established oncogenic role in a large variety of cancers." (PMID 32873321, 2020). "Ongoing trials investigating EZH2 inhibitors in multiple cancer types as described in this review will provide insight to this question, however, accurate biomarkers of response to EZH2 inhibition will be of paramount importance in deciphering this question." (PMID 33050946, 2020). "In this review, we summarize the structure and action modes of EZH2, focusing on up-to-date findings regarding the role of EZH2 in cancer initiation, progression, metastasis, metabolism, drug resistance, and immunity regulation." (PMID 32723346, 2020). "EZH2 overexpression has been shown to correlate with aggressiveness and advanced disease in several cancer types." (PMID 34968293, 2020). "As the catalytic core component, Enhancer of Zeste Homolog 2 (EZH2) has been extensively analyzed, particularly because dysregulation of EZH2 is strongly oncogenic and has been observed in various cancers, making this protein an interesting therapeutic target." (PMID 32650416, 2020). "Our results are in accordance with previous studies illustrating that EZH2 regulates gefitinib resistance in cancer cells." (PMID 33056982, 2020). "Mechanistically, miR-25 and miR-30d reduced cancer cells growth and proliferation by targeting the expression of oncogene, polycomb protein enhancer of zeste 2 (EZH2)." (PMID 33126409, 2020). "Many cancers are known to feature very high EZH2 expression levels, so this protein has emerged as an anticancer target for which multiple chemical inhibitors have been developed." (PMID 32873321, 2020). "EZH2 is frequently overexpressed in several cancers, promoting cancer cell-proliferation and -survival." (PMID 33137873, 2020). "Currently, the role of EZH2 in the pathogenesis and development of malignant tumors has been studied extensively." (PMID 32448308, 2020). "The recent studies have shown that EZH2 regulates diverse cellular processes and participates in cancer development, progression and metastasis." (PMID 32242003, 2020). "This drug is indeed described as one of more specific inhibitor of EZH2, and is currently tested in clinical trials for the treatment of cancer." (PMID 33177650, 2020). "We found that EZH2 repressed the miR-139 expression pattern by recruiting H3K27me3 to promote miR-139 promoter methylation, while silencing of EZH2 suppressed in vitro cancer progression by increasing miR-139." (PMID 33292225, 2020). "As a stemness factor, EZH2 possesses the ability to regulate cell differentiation, embryonic development and cancer development, such that EZH2 silencing demonstrably down-regulates various genes in ESCC." (PMID 33330444, 2020).
cancer (continued). "Overexpression of EZH2 is observed in numerous cancer of different origin and its inactivation was therapeutically effective in several cancer models." (PMID 32880874, 2020). "Involvement of the EZH2 protein in the migration and invasion processes of cancer has also been highlighted with various lncRNAs." (PMID 33050646, 2020). "In other cancers, lncRNAs also have been reported to interact with EZH2, which promote cancer cell migration." (PMID 33050646, 2020). "To determine its oncogenic role in HCC, we first examined the expression level of EZH2 in multiple cancers by analyzing GEPIA (Gene Expression Profiling Interactive Analysis) data set and RNA-seq data set retrieved from The Cancer Genome Atlas (TCGA) database." (PMID 33168810, 2020). "Promoter methylation of the CpG islands of RUNX3 and overexpression of enhancer of zeste homolog 2 (EZH2) has been suggested to downregulate RUNX3 in cancer." (PMID 32943993, 2020). "In cancer, EZH2 was shown to redirect HOTAIR, to metastasis suppressor protocadherin genes, PCHD5 and PCHD10 and increase the H3K27me3 mark to silence gene expression." (PMID 33246425, 2020). "A series of studies demonstrated that EZH2 can promote cancer tumorigenesis and metastasis independent on PRC2-mediated target gene silencing." (PMID 33308321, 2020). "As EZH2 is an epigenetic regulator important for cancer development and progressionacross various tumors, the abundance and activity of EZH2 should be finelycontrolled depending on the various signals and pathophysiological conditions ofcells." (PMID 32453339, 2020). "Overexpression of a phospho-T367-deficient mutant of EZH2 (T367A) inhibits its cytoplasmic localization and disrupts EZH2 interaction with cytoskeletal proteins, hence reducing the EZH2-related cancer cell invasion and spontaneous metastasis." (PMID 33327550, 2020). "An increase in the expression of EZH2 has been identified as a key role in cancer progression and drug resistance." (PMID 32117705, 2020). "In vitro and in vivo trials have confirmed that GSK126, an EZH2 inhibitor, rescues the expression of downregulated genes in MLL3 knockdown cells, indicating that EZH2 represents a potential therapeutic target for MLL3 mutant cancers." (PMID 33008426, 2020). "Although DZNep treatment has been shown to inhibit effector CD8+ T cell function, an interpretational caveat is advised as this drug broadly inhibits methyltransferases and is known to have non-EZH2 mediated effects in cancer cells." (PMID 33117406, 2020). "Piling studies have highlighted that EZH2 participates in cancer cell proliferation by regulating several cell cycle-related genes." (PMID 33121524, 2020). "Studies have shown that the downregulation of miRNA-101 or miRNA-298 results in the overexpression of EZH2, thereby resulting in cancer progression." (PMID 33163485, 2020). "EZH2 has been shown to be essential for proliferation of cancer cell lines that is largely dependent upon its methyltransferase domain." (PMID 32477007, 2020). "Detailed analysis of the EZH2 ultra-high cohort revealed that all these cancers in fact, exhibited platinum-hypersensitivity and were without exception advanced high-grade tumors." (PMID 33230143, 2020). "Previous studies have shown that MEK-ERK depletion reduced the expression of EZH2 in cells with KRAS (G12C) mutation, thereby reducing the level of histone methylation and inhibiting the development of cancer." (PMID 32903217, 2020). "Recently, MALAT1 was reported to bind EZH2 in many types of cancer, indicating the important regulatory relationship between these two elements." (PMID 32972446, 2020). "EZH2 can also induce an epithelial-to-mesenchymal transition in the cancer cells, increases their metastatic potential and acts as a coactivator for transcription factors including the androgen receptor." (PMID 32850962, 2020).
cancer (continued). "EZH2 represses the expression of tumor suppressor genes in various cancer cells, thereby promoting cell invasion and driving tumor progression." (PMID 32117960, 2020). "In turn, pRb-E2F negatively regulates EZH2 transcript accumulation and proliferation; conversely high expression of EZH2 is observed in cancer stem cells as has a critical function in regulating stem cell expansion and maintenance." (PMID 32664691, 2020). "As there are many important roles of EZH2 in cancer, therapies targeting EZH2 have been important strategies in treatment of many types of cancer." (PMID 32723346, 2020). "Within lung tumor samples, LAT1 and EZH2 were co-expressed in cancer cells that were more undifferentiated and highly proliferative, compared with adjacent stromal tissues that did not express these proteins." (PMID 33086625, 2020). "Previous studies have demonstrated the correlation between the chromatin modifier Enhancer of Zeste Homolog 2 (EZH2) and cancer tumorigenesis and metastasis." (PMID 33308321, 2020). "Enhancer of zeste homolog 2 (EZH2), an oncogene, is a commonly up‐regulated epigenetic factor in human cancer." (PMID 32725802, 2020). "Given the evidence for EZH2 enzymatic gain-of-function being a cancer driver, development of specific EZH2 inhibitors (EZH2is) has received widespread attention." (PMID 32477007, 2020). "As mentioned, altered expression of EZH2 in ERMS and SS has been linked to cancer survival and to retention of a less differentiated and more aggressive phenotype." (PMID 32532153, 2020). "Inhibition of EZH2 suppresses cancer cell proliferation and invasion, and as such EZH2 seems to be a potential therapeutic target." (PMID 32873863, 2020). "EZH2 can also indirectly induce aerobic glycolysis in cancer cells by suppressing the expression of some microRNAs." (PMID 32448308, 2020). "Previous studies have indicated that EZH2 can epigenetically silence microRNAs in different cancer types and neural stem/progenitor cells." (PMID 33168810, 2020). "EZH2 inhibitors are therefore expected to induce cancer cell differentiation and reduced activity of cancer stem cells." (PMID 33339101, 2020). "Then, we immunohistochemically detected the expression of SMAD2 and EZH2 in 20 pairs of TNBC samples and paired paracancer specimens and found that the expression levels of SMAD2 and EZH2 were significantly increased in cancer tissues." (PMID 33330073, 2020). "EZH2, as a master regulator of transcription, plays a critical role in occurrence and progression of human cancers." (PMID 32849835, 2020). "Previous studies have demonstrated that overexpression of EZH2 is related to poor prognosis in various cancers." (PMID 33180829, 2020). "It is worth noting that all tumors classified as ultra-high EZH2 expressing were all high-grade cancers." (PMID 33230143, 2020). "Considering the strong associations between EZH2, KDM6A, KDM6B and development, the link between these proteins and cancer cell plasticity will continue to become more apparent." (PMID 33003334, 2020). "The role of EZH2 in cancer progression and malignancy has been extensively studied in the last decade." (PMID 33304896, 2020). "For comparison, in the stage-adjusted cohort of high-grade cancers with lower EZH2 expression, the rate of platinum-hypersensitivity was as low as 17.5% (data not shown)." (PMID 33230143, 2020). "Studies in the last decade have demonstrated a wide variety ofchanges in EZH2 and its partners in cancer." (PMID 33456979, 2020). "The crucial involvement of EZH2 in carcinogenesis has beenreported in various types of tumors, thus making it an attractive therapeutic targetfor cancer treatment." (PMID 32453339, 2020). "This discovery ultimately led to the identification of small molecule inhibitor of EZH2 as potential therapy for this deadly cancer." (PMID 32182803, 2020).